MAP2K2 (mitogen-activated protein kinase kinase 2)
Description:
Catalyzes the concomitant phosphorylation of a threonine and a tyrosine residue in a Thr-Glu-Tyr sequence located in MAP kinases. Activates the ERK1 and ERK2 MAP kinases (By similarity). Activates BRAF in a KSR1 or KSR2-dependent manner; by binding to KSR1 or KSR2 releases the inhibitory intramolecular interaction between KSR1 or KSR2 protein kinase and N-terminal domains which promotes KSR1 or KSR2-BRAF dimerization and BRAF activation.
Synonyms: MEK2; MKK2; PRKMK2; CFC4; MAPKK2
Tractability: Small molecule: an approved drug acts on it; a structure with a bound ligand is known; a high-quality ligand is known; it has a high-quality binding pocket; it belongs to a druggable protein family. Antibody: UniProt places it where antibodies can reach, with high confidence. PROTAC: it is named in the literature on targeted protein degradation; ubiquitination databases record sites on it; its protein half-life has been measured; a small molecule that binds it is known.
Target class: STE protein kinase group; Kinase; Enzyme; Protein Kinase; STE protein kinase STE7 family
Chemical probes: TRAMETINIB (high quality)
Gene: Protein-coding gene on chromosome 19 (4,090,317 to 4,124,216, reverse strand). Ensembl gene ENSG00000126934.
Subcellular location: Cytoplasm; Membrane
Subcellular location (Human Protein Atlas): Cytosol; End piece; Mid piece; Principal piece
Pathways (Reactome):
Disease: Paradoxical activation of RAF signaling by kinase inactive BRAF; Signaling by BRAF and RAF1 fusions; Signaling by MAP2K mutants; Signaling by RAF1 mutants; Signaling by high-kinase activity BRAF mutants; Signaling by moderate kinase activity BRAF mutants; Signaling downstream of RAS mutants; Uptake and function of anthrax toxins
Signal Transduction: Frs2-mediated activation; MAP2K and MAPK activation; MAPK1 (ERK2) activation; Negative feedback regulation of MAPK pathway; RAF activation
Developmental Biology: Signal transduction by L1
Gene Ontology:
Molecular function: MAP kinase kinase activity; MAP-kinase scaffold activity; PDZ domain binding; protein binding; protein serine kinase activity; protein serine/threonine kinase activator activity; protein tyrosine kinase activity; scaffold protein binding; protein serine/threonine kinase activity; protein serine/threonine/tyrosine kinase activity; ATP binding; protein kinase activity
Biological process: ERK1 and ERK2 cascade; peptidyl-serine autophosphorylation; positive regulation of DNA-templated transcription; positive regulation of gene expression; positive regulation of protein serine/threonine kinase activity; MAPK cascade; regulation of early endosome to late endosome transport; regulation of Golgi inheritance; regulation of stress-activated MAPK cascade
Cellular component: cell-cell junction; cytoplasm; cytoplasmic side of plasma membrane; cytosol; endoplasmic reticulum; Golgi apparatus; membrane; microtubule; perinuclear region of cytoplasm; peroxisomal membrane; early endosome; extracellular region; focal adhesion; late endosome; mitochondrion; nucleus
Genetic constraint (gnomAD): Loss-of-function variants: 25 observed, 40.72 expected, observed/expected ratio (o/e) 0.61, 90% interval 0.45 to 0.86. The upper end of that interval is the gene's LOEUF score, 0.86, which puts it in group 3 of 6, group 1 being the genes least tolerant of losing a copy. Missense variants: 470 observed, 508.63 expected, observed/expected ratio (o/e) 0.92, 90% interval 0.86 to 1. Synonymous variants: 244 observed, 212.24 expected, observed/expected ratio (o/e) 1.15, 90% interval 1.03 to 1.28.
Gene-disease validity (ClinGen):
ClinGen rates the evidence that MAP2K2 causes each of these diseases.
cardiofaciocutaneous syndrome (autosomal dominant): Definitive. Cardiofaciocutaneous (CFC) syndrome is a RASopathy characterized by craniofacial dysmorphology, congenital heart disease, dermatological abnormalities (most commonly hyperkeratotic skin and sparse, curly hair), growth retardation and intellectual disability.
Noonan syndrome (autosomal dominant): Limited. Noonan Syndrome (NS) is characterized by short stature, typical facial dysmorphism and congenital heart defects.
Cancer hallmarks: angiogenesis; tumour promoting inflammation (suppresses); invasion and metastasis (promotes); proliferative signalling (promotes); escaping programmed cell death (promotes); change of cellular energetics
Homologues: Orthologues: chimpanzee MAP2K2 (100% identical), pig MAP2K2 (97% identical), guinea pig MAP2K2 (94% identical), mouse Map2k2 (94% identical), rat Map2k2 (94% identical), macaque MAP2K2 (92% identical), zebrafish map2k2a (86% identical), zebrafish map2k2b (82% identical), dog MAP2K2 (77% identical), Drosophila melanogaster Dsor1 (61% identical), Caenorhabditis elegans mek-2 (53% identical). Paralogues in human: MAP2K1 (80% identical), MAP2K5 (38% identical), MAP2K7 (34% identical), MAP2K4 (34% identical), MAP3K4 (24% identical), MAP3K2 (22% identical), MAP3K3 (22% identical), NEK1 (14% identical).
Diseases named in the same sentence as MAP2K2 in open-access papers:
MAP2K2 is named in the same sentence as 142 diseases in open-access papers, as found by Europe PMC text mining. Sharing a sentence is not in itself a finding about the gene and the disease. The quoted sentences say what the papers report.
melanoma (50 papers, 2011 to 2025). A malignant, usually aggressive tumor composed of atypical, neoplastic melanocytes. "Moreover, the coexistence of mutated BRAF and gain-of-function MAP2K1/MAP2K2 mutations was detected in two melanomas and resulted in higher resistance to MEK inhibitors." (PMID 32847629, 2020). "The results so far suggest that some mutations in the MAP2K1 and MAP2K2 genes may contribute to the primary resistance of melanoma cells to targeted therapy and should be further investigated both functionally and in clinics as a part of the genetic predictive panel." (PMID 35565444, 2022). "A number of melanoma recurrent mutations have been reported in the literature in several genes including KIT, TERT, MAP2K1 and MAP2K2, RAC and PPP6C." (PMID 36765773, 2023). "There have been several studies that have investigated the role of somatic mutations in MAP2K1 and MAP2K2, and in MAP3K5 and MAP3K9 in melanoma." (PMID 37504268, 2023). "Previous studies have documented how the use of a MAP2K2 inhibitor for BRAF-mutated melanoma triggers the PI3K/AKT pathway and leads to drug treatment resistance, although acquired MAP2K2 mutations have also been associated with the drug resistance." (PMID 35215249, 2022). "In another study of 127 melanomas, eight had MAP2K1 point mutations and two had MAP2K2 point mutations; these alterations were associated with constitutive ERK phosphorylation, and most co-occurred with either BRAF or NRAS mutation." (PMID 32483240, 2020). "Sequencing of seven melanoma cell lines and donor-matched germline cells found MAP2K1 and MAP2K2 (MEK1 and MEK2, respectively) mutations, resulting in constitutive ERK phosphorylation and higher resistance to MEK inhibitors." (PMID 24743024, 2014). "Screening of a larger cohort of melanoma tumors revealed the presence of recurring somatic MAP2K1 and MAP2K2 mutations at an overall frequency of 8%." (PMID 24743024, 2014). "YTHDF2 was identified to promote multiple melanoma cell proliferation via STAT5A/MAP2K2/p-ERK axis." (PMID 37256443, 2024). "Some studies have also shown that targeting MAP2K1 and MAP2K2, and MAP3K5 and MAP3K9 with specific drugs can be effective at inhibiting the growth of melanoma cells in preclinical models." (PMID 37504268, 2023). "Among 253 melanomas, 129 (51.0%) BRAF, 45 (17.8%) NRAS, 6 (2.4%) KIT, 4 (1.6%) GNAQ, 2 (0.8%) GNA11, 2 (0.8%) MAP2K1 and no MAP2K2 gene mutations were detected by the biochip assay." (PMID 28881731, 2017).
breast cancer (18 papers, 2014 to 2025). A primary or metastatic malignant neoplasm involving the breast. "The protein expression of RAD52, RAD50, PBX2, MAP2K2 (MEK2), and S100P was also validated with immunohistochemistry in invasive breast cancer tumor tissues." (PMID 37445737, 2023). "Thus, to confirm this, we focused on the expression of Map2k2 (MEK) in the mammary tumor tissue." (PMID 37699010, 2023). "Selumetinib, another potential candidate targeting MAP2K1 and MAP2K2, has demonstrated efficacy in suppressing cell proliferation and migration in various cancers, including HER2-positive breast cancer." (PMID 40004024, 2025). "The protein expression of FGF-2, RAD52, RAD50, PBX2, MAP2K2 (MEK2), and S100P was also validated with immunohistochemistry in invasive breast cancer tumor tissues." (PMID 37445737, 2023). "IRF5, MAP2K2 (MEK2), and S100P had concordant overexpressed mRNA in invasive breast cancer tissues and blood samples." (PMID 37445737, 2023). "Twenty of the 27 common genes have published data presenting that these genes were associated with breast cancer, but seven genes (DUSP10, GABRA6, GABRR1, KIF21B, KLHL24, MAP2K2, and SLC10A1) might be passenger genes or have not yet been studied regarding their pathological roles in breast cancer." (PMID 28973975, 2017).
RASopathy (17 papers, 2014 to 2026). Developmental syndromes caused by germline mutations (or in rare cases by somatic mosaicism) in genes that alter the Ras subfamily and mitogen-activated protein kinases that control signal transduction. "Cardiofaciocutaneous syndrome type 4 (CFC4), a RASopathy caused by pathogenic variants in MAP2K2, presents with characteristic dermatologic, craniofacial, and multisystem findings." (PMID 41522845, 2026). "Many of the RASopathy-associated genes are in gene families: RAF (BRAF and RAF1), RAS (HRAS, KRAS, MRAS, NRAS, RIT1, and RRAS2), MAP2K (MAP2K1 and MAP2K2), and SOS (SOS1 and SOS2)." (PMID 40496714, 2025). "MAP2K2 plays an important role in the RAS signaling pathway, and germline variants in this pathway lead to RASopathies." (PMID 40995433, 2025). "CFC syndrome is a RASopathy associated with germline mutations in KRAS, BRAF (non-V600E) and MAP2K1 (MEK1)/MAP2K2 (MEK2)." (PMID 33800195, 2021). "We provide genetic and biochemical evidence that dysregulation of Fgfr4, Hras and Map2k2 in the heart of Rreb1 heterozygous mice is deleterious leading to a cardiomyopathy that is reminiscent of the phenotype observed in Noonan-like RASopathies." (PMID 32938917, 2020). "Cardio-facio-cutaneous syndrome (CFC) is a rare RASopathy associated with mutations in BRAF, KRAS, MEK1 (MAP2K1) and MEK2 (MAP2K2)." (PMID 29590634, 2018). "On these bases, theseauthors proposed that haploinsufficiency of MAP2K2/MEK2 "appears to bea new model of a RASopathy, where a deletion of one of the components of the pathway,MEK2, results in a RASopathy-like phenotype" (Nowaczyket al., 2014)." (PMID 27561113, 2016). "In 2013, haploinsufficiency of MAP2K2/MEK2 was proposed as a novel mechanism for the pathogenesis of RASopathies." (PMID 24739123, 2014). "In addition, we verified by exomeanalysis that the patient did not have any pathogenic variants in the genes associatedwith Noonan Syndrome and other rasopathies (PTPN11,SHOC2, KRAS, CBL,SOS1, RAF1, HRAS,NRAS, RASA1, SPRED1,BRAF, MAP2K1, MAP2K2, RIT1 andRRAS)." (PMID 27561113, 2016). "Furthermore, happloinsufficency of MAP2K2/MEK2 was recently reported be a novel mechanism for the etiology of RASopathies." (PMID 24739123, 2014). "Multigene panel for common RASopathy genes that includes BRAF, MAP2K1, MAP2K2, KRAS and YWHAZ usually detects up to 90% of individuals with CFC and it is the preferred initial test." (PMID 38136934, 2023). "Germline mutations in MAP2K1 (which encodes MEK1) and MAP2K2 (MEK2) can cause cardio-facio-cutaneous (CFC) syndrome, a known RASopathy, although there are no reports of bAVMs in these patients." (PMID 39899215, 2025). "For the RASopathy genes, no protein structures were available for RAF1, MAP2K2, or SHOC2 (9 total variants)." (PMID 25802880, 2015). "In distinction to the known RASopathies, which are single gene disorders, the 6p25.1p24.3 microdeletion syndrome arises via transcriptional dysregulation of multiple RREB1 target genes including FGFR4, HRAS and MAP2K2 that result in sensitization of the MAPK pathway to activation." (PMID 32938917, 2020).
cardiofaciocutaneous syndrome (13 papers, 2010 to 2022). "Of the remaining five patients, three patients were found to have PKHD1 variants associated with autosomal recessive PKD (ARPKD), and two carried MAP2K2 variants associated with cardio-facio-cutaneous syndrome." (PMID 35099770, 2022). "The MAP2K2 gene is known to be related with dominant inherited cardio-facio-cutaneous syndrome in humans, but it was so far unknown to cause a similar disease in domestic animals." (PMID 34209498, 2021). "High and narrow palate with submucous clefting is a typical craniofacial feature in cardiofaciocutaneous syndrome, which is caused by mutations in KRAS, BRAF, MAP2K1 and MAP2K2." (PMID 34897389, 2022). "Currently, dominantly inherited mutations in four genes have been associated with CFC syndrome: BRAF, MAP2K1, MAP2K2, and KRAS." (PMID 34209498, 2021).
colorectal cancer (11 papers, 2008 to 2026). A primary or metastatic malignant neoplasm that affects the colon or rectum. "As a result, epidermal growth factor (EGF), MAP2K2, MCC (mutated in colorectal cancer), and NRAS (neuroblastoma RAS viral oncogene homolog) were determined as remarkably prognostic-related genes." (PMID 33553243, 2020). "The oncogenes MAP2K2 and KRAS exhibited changes in isoform proportions, despite no significant alterations in their overall gene expression levels, which indicates that their distinct RNA isoforms may have different functions in colorectal cancer." (PMID 40702779, 2025).
lung carcinoma (10 papers, 2012 to 2025). "Analysis of human lung cancer data sets derived from The Cancer Genome Atlas (TCGA) showed that KRAS, RAF1, MAP2K1, MAP2K2, MAPK3, and MAPK1 expression levels were positively correlated with the BCL6 expression level." (PMID 36377663, 2022). "Meanwhile, the MAP2K1 and MAP2K2 genes regulate cell proliferation and survival through the MAPK signaling pathway, and their abnormal activation drives tumor growth, metastasis, and drug resistance in lung cancer, making them critical therapeutic targets." (PMID 40136480, 2025).
colon carcinoma (7 papers, 2008 to 2024). "The inhibition of MAP2K2 may suppress not only the formation of colon cancer but also the progression of colon cancer and its metastasis to the liver and lung." (PMID 39334689, 2024). "The changes in splicing fidelity elicited by SRPK1 down-regulation in breast and colon tumor cells have been shown to lead to production of aberrant MAP2K2 transcripts and protein, which in turn may reduce the availability of this kinase to phosphorylate its targets MAPK1/2." (PMID 23236423, 2012). "MAP2K2 (also known as MEK2), part of the Kras/Braf/MEK/MAPK signaling pathway, plays a vital role in inducing cell survival and proliferation and the inhibition of cell apoptosis of colon cancer." (PMID 39334689, 2024). "Furthermore, molecular docking results indicated the stable binding connections between TQ/5-FU and the hub targets, i.e., MAP2K2, CASP3, PIK3CA, ESR1, CYP3A4, CYP2C19, and CYP2C9, suggesting that TQ, in combination with 5-FU, may treat colon cancer by modulating these hub targets." (PMID 39334689, 2024).
Noonan syndrome (7 papers, 2016 to 2025). "In Noonan syndrome, KDM1A could affect the histone methylation level of the MAP2K2 promoter region." (PMID 36689133, 2023).
glioma (6 papers, 2022 to 2025). A benign or malignant brain and spinal cord tumor that arises from glial cells (astrocytes, oligodendrocytes, ependymal cells). "Regarding its relationship with cancer, studies have already demonstrated that SNHG25 positively regulates the upregulation of MAP2K2 in glioma cells and tissues by sponging miR-579-5p." (PMID 40894525, 2025). "Our results suggest that the assessment of mRNA BDKRB1, PRKAR1A, MAP2K2, and EGFR by RT-qPCR in samples of patients with gliomas may have diagnostic significance." (PMID 38254732, 2024).
Costello syndrome (5 papers, 2012 to 2023). Costello syndrome (CS) is a rare multisystemic disorder characterized by failure to thrive, short stature, developmental delay or intellectual disability, joint laxity, soft skin, and distinctive facial features. "Mutations in MAP2K2 and HRAS are responsible for cardiofaciocutaneous (CFC) and Costello syndrome, respectively, related monogenic disorders characterized by mental retardation, facial dysmorphism, cardiac defects and a high prevalence of autistic features." (PMID 22558107, 2012). "CFC and Costello syndromes are thought to be caused by gain-of-function mutations that activate the Ras/ERK pathway, whereas the MAP2K2 and HRAS variants that we identified in autism cases are most compatible with loss of protein function." (PMID 22558107, 2012). "The remaining genes involved were RAF1 (three patients, all with Costello syndrome suspicion), RIT1 (two patients), BRAF (one patient), MAP2K1 (three patients), MAP2K2 (two patients), PTPN11 (two patients), SOS1 (one patient), and SHOC2 (three patients, two of them with Costello syndrome suspicion)." (PMID 37568403, 2023).
pancreatic cancer (5 papers, 2015 to 2022). "When similar analyses were performed with breast, colonic, and pancreatic carcinoma lineages, the SRPK1 knockdown impacted the expression of MAP2K2 instead of MAP2K1, providing additional evidence for this different response according to each cell line." (PMID 26244849, 2015).
Alzheimer disease (4 papers, 2023 to 2025). A progressive, neurodegenerative disease characterized by loss of function and death of nerve cells in several areas of the brain leading to loss of cognitive function such as memory and language. "MAP2K2 (MAP kinase) upregulation is associated with the hyperphosphorylation of tau, contributing to the development of Alzheimer’s disease." (PMID 38002279, 2023). "Seven of these genes are Alzheimer’s disease-related, six are down-regulated with both Apoer2-ICDs (COX7A2L, FZD2, KIF5A, MAP2K2, PSENEN, RAF1) and one with only the Apoer2-ICD[Δ19] (SLC39A9)." (PMID 37461529, 2023).
thyroid cancer (4 papers, 2020 to 2026). "The combination of hsa-miR-4732-5p and hsa-miR-1180-3p as an input for pathway analysis provided “thyroid cancer” as an altered pathway (P = 0.037), including MAP2K2, CDKN1A, and TRP as target genes." (PMID 36583003, 2022). "We verified the correlation between TNK2, DYK1B, MAP2K2 and MOF expression in the TCGA database, and found that in thyroid cancer cells, they all had a strong positive correlation with MOF expression." (PMID 33519470, 2020).
COVID-19 (3 papers, 2022 to 2024). A disease caused by infection with severe acute respiratory syndrome coronavirus 2. "The gilteritinib and RAF, omipalisib, RO5126766, sorafenib, MEK or MAP2K2 and pictilisib are all possible treatments for COVID-19." (PMID 38827795, 2024). "Several enzymes can be used as a target for COVID-19 therapeutics including PI3K ̧ mTOR, growth factor receptor, RAF, MAP2K2, FLT3, AXL, AKT, and matrix metalloprotease MMP2 and MMP9." (PMID 35251015, 2022).